ARG2 (arginase 2)
Diseases named in the same sentence as ARG2 in open-access papers (continued):
Sharing a sentence is not in itself a finding about the gene and the disease.
tumor (continued). "In this study, we examined the expression of two major enzymes involved in arginine depletion and replenishment in the tumor microenvironment, namely ARG2 and ASS1, respectively, in a series of non-small-cell lung carcinomas (NSCLC)." (PMID 34344457, 2021). "Both tumor‐infiltrating neutrophils and monocytes expressed Arginase 2, CD39 and CD73, IL10, iNOS, and Ptgs2 at increased levels compared to circulating cells." (PMID 31793740, 2020). "In turn, ARG2 knockout increased the expression of TCRζ on co-cultured Jurkat cells, implying arginase 2 in promotion of tumor growth and immune evasion." (PMID 32932854, 2020). "Increased ARG2 expression and a diminished number of tumor-infiltrating lymphocytes was also reported in prostate cancer." (PMID 32707920, 2020). "Single cell RNA-Seq of patient lung tumors showed very little ARG1 in general and was elevated mainly in B cells, myeloid cells or minor group of T cells in the tumor, while ARG2 was expressed across several cell types both in normal tissue and tumors." (PMID 30728077, 2019). "Since the biological functions of ARG1 and ARG2 are identical, silencing of ARG2 (tumor suppressor) was replenished by the excessive amount of PEGylated ARG1 (BCT-100) that caused arginine depletion and suppression of tumor growth." (PMID 30808864, 2019). "Apart from their role in infiltrating myeloid cells, recent reports suggest that tumour cells can also deplete arginine by expressing ARG2, either intra− or extracellularly." (PMID 30307989, 2018). "We also assessed gene expression of various factors associated with the suppressive function of MDSCs including S100A8, S100A9, Nos3, Arg1 and Arg2 in BM-MDSCs compared to G-MDSCs from the tumor, spleen and lungs of tumor-bearing mice." (PMID 29677215, 2018). "When PDA cells were grown as orthotopic xenografts in lean or obese mice, a moderate decrease in tumor volume was noted in lean mice upon ARG2 knockdown (1.7-fold)." (PMID 28808255, 2017). "In order to review the role of Arg2, it is important to outline the nature and function of MDSCs in tumor biology and autoimmune pathology." (PMID 28191010, 2017). "COL2A1 and FMOD showed very similar expression patterns as ARG2 across sample groups defined by tissue and age status, demonstrating a higher expression level in the young tumor group than in the old tumor group." (PMID 28027300, 2016). "ARG2 catalyses the conversion of arginine to ornithine, which is a precursor for the synthesis of polyamines that control growth of benign and tumor cells of the prostate." (PMID 21347291, 2011). "Reciprocally, androgen deprivation and ADT reduced ARG2 expression in vitro and in the primary tumor of PCa patients, respectively." (PMID 20711410, 2010). "Collectively, these results suggest that ARG1 and ARG2 expressed by LNCaP cells are enzymatically active and participate in important physiological processes such as cellular proliferation and tumor-derived immunosuppression." (PMID 20711410, 2010). "In HER2-positive disease, our findings associate genes such as ARG2, S100A1, MT2A, EIF4EBP1, KLF4, BTG3, and BAG1 to be associated with favourable prognosis through their roles in metabolic regulation, oxidative stress mitigation, and tumour suppression." (PMID 41007296, 2025). "Cytomegalovirus might serve as a causative agent in GBM through ARG2 upregulation and STAT3 signaling, which is often used as an early tumor biomarker." (PMID 40558592, 2025). "Also, Cancer-associated fibroblasts (CAFs) can suppress anti-tumor immunity by rewiring T-cell metabolism, chiefly through Indoleamine 2,3-dioxygenase (IDO) and Arginase 2 (ARG2)." (PMID 40940809, 2025). "Related Arg2 mRNA level was also decreased in tumor nodules." (PMID 37996700, 2024). "In addition, both germline deletion of the Arg2 gene in mice and the adoptive transfer of Arg2-deficient CD8+ T cells significantly improve the anti-tumor effect in pre-clinical cancer models." (PMID 38539506, 2024).
tumor (continued). "In accordance with their physiological tissue distribution, expression of ARG1 by tumor cells is mainly limited to hepatocellular carcinoma, while ARG2, although largely understudied compared to ARG1, is found in the neoplastic cells of several human cancer types." (PMID 39211039, 2024). "Cytomegalovirus could present as a causative agent to GBM through ARG2 upregulation and STAT3 signaling, which is often used as an early tumor biomarker." (PMID 38612552, 2024). "In a Lewis lung cancer tumor model, they found that vaccines with these peptides significantly inhibited tumor growth by activating ARG2-specific T cell response, which may constitute a future potential for a new therapeutic candidate in immunotherapy." (PMID 39337272, 2024). "Indeed, lactate induces the release of VEGFA as well as arginase 1 (ARG1) and arginase 2 (ARG2), which dampen the activity of other immune cells and ultimately accelerate tumor progression." (PMID 38730724, 2024). "ARG2 stimulates the metastasis of tumours in melanoma via the H2O2-STAT3 pathway." (PMID 39051546, 2024). "Reduced ARG2 activity has been found to promote ccRCC tumour growth through multiple mechanisms." (PMID 38136342, 2023). "Furthermore, ARG1- or ARG2-based vaccination in several murine models of cancer can activate specific T cells and induce tumor growth control." (PMID 36175673, 2023). "The fact that the dysregulation of the ureagenic cycle represents a distinctive feature of ccRCC is supported by the low levels of mRNA and the altered expression and function of representative enzymes (ASS1, ASL, ARG2) in tumour samples compared to normal kidney tissue." (PMID 38136342, 2023). "This study also revealed the immune–metabolic regulatory loop between tumor cells and infiltrating myeloid cells regulating ARG2 expression in vitro, which could be clinically exploited." (PMID 37445845, 2023). "Furthermore, ARG2 deletion in CD8+ T cells has a considerable synergistic effect with PD-1 blockade in controlling tumour growth and animal survival, strongly suggesting that ARG2 is a valuable target for T cell-based cancer immunotherapies." (PMID 36010962, 2022). "Therefore, these three key MVIRGs (DBF4, ARG2, and SLC16A3) are closely associated with the tumor and its prognosis, which also proves the correctness of choosing these three MVIRGs to establish a prognostic model to a certain extent." (PMID 34975331, 2022). "However, adoptive transfer of Arg2−/− CTLs was also more efficient at clearing tumours and synergised with PD-1 blockade, suggesting that CTL-intrinsic ARG2 activity contributes to the suppression of their anti-tumour activity." (PMID 33401460, 2021). "It has been anticipated that consumption and depletion of ARG from the tumor stroma due to the overexpression of ARG2 by CAFs would be detrimental for cancer cells, which contrasts the clinical aggressiveness of tumors with high stroma ARG2 expression, as found in the current study." (PMID 34344457, 2021). "Besides IDO1 and Arg 1, other amino acid degrading enzymes such as tryptophan 2,3-dioxygenase and arginase 2, has relevance in the regulation of tumor-induced immune tolerance, including the induction of an immunosuppressive tumor microenvironment." (PMID 34389039, 2021). "The RNAseq analysis of four null cell PitNETs and four silent subtype III PitNETs which were more clinically aggressive, demonstrated altered gene expression in tumor microenvironment and immuno-surveillance regulation, e.g., arginase type II (ARG2), semaphorin-3A (SEMA3A), and some HLA genes." (PMID 33808624, 2021). "As the importance of repressing mitochondrial ARG2 as a metabolic tumor suppressor in ccRCC has been established, we now focused on the cytosolic urea cycle enzymes ASS1 and ASL that convert citrulline and aspartate to arginine and fumarate via argininosuccinate." (PMID 34861885, 2021).
tumor (continued). "Taken together, these observations suggest that the intracellular arginine concentration and its regulation by Arg2 dictate Treg expansion and survival in different microenvironments, and unveil Arg2 as a putative therapeutic target in both autoimmune and neoplastic diseases." (PMID 34037806, 2021). "Silencing of ARG2 increased cell viability and indicated that ARG2 might be a tumor suppressor in vitro." (PMID 30808864, 2019). "High-endogenous ARG2 in tumor cells may lower the intratumoral arginine level similar to ARG1 treatment with cells adapting to a low intratumoral arginine environment." (PMID 30808864, 2019). "We propose that high-endogenous expression of ARG2 could impede the anti-tumor effect of PEGylated ARG1 in lung SCC." (PMID 30808864, 2019). "Whether ARG2 is involved in the effect of ARG1 on tumor growth still requires further exploration in the future." (PMID 30320132, 2018). "In this scenario, the use of Arg2 inhibitors to treat cancers becomes arguable since the inflamed normal tissue—adjacent to the tumor—might develop worsened immunopathology when Arg2 is inhibited." (PMID 28191010, 2017). "In addition, the presence of ARG2-expressing stromal cells was closely correlated with higher tumor-infiltrating CD68+ macrophages and CD66b+ neutrophils, and lower tumor-infiltrating CD4+ T cells and CD8+ T cells." (PMID 23424623, 2013). "Arginase 2 (ARG2) expression by PCa cells leads to a reduced activation of tumor-specific T cells." (PMID 20711410, 2010). "Moreover, in STS, both ARG1 and ARG2 gene expression have been identified in tumor samples, suggesting an immunosuppressive TME that may impede an effective immune response." (PMID 39502689, 2024). "Furthermore, in vitro studies indicate that inhibition of ARG2 may even be beneficial for the anti-tumor T cell response, whereas it may also directly inhibit the growth of ARG2-expressing tumors." (PMID 39211039, 2024). "ARG1 is a cytoplasmic protein, while ARG2 is mainly localized in the mitochondria, closely associated with poor prognosis through degradation of L-arginine and thus inhibiting the anti-tumor effects of various types of cells in TME antitumor effects and promotes tumor cell proliferation." (PMID 39239650, 2024). "The exact role of arginase 2 in tumor survival remains unknown." (PMID 37749499, 2023). "Consequently, ARG2 inhibition led to ammonia accumulation and suppressed tumor growth." (PMID 37648285, 2023). "Additionally, environmental hypoxia is known to affect ARG2 expression, and thus, the differential oxygen tensions between a hypoxic tumour and a highly vascularized psoriatic lesion might result in altered ARG2 induction between disease states." (PMID 36010962, 2022). "Finally, to determine whether OATD-02 can act independently of the immune response by inhibiting the intracellular ARG2 expressed by human tumour cells, we tested the effects of OATD-02 on the survival of leukemic K562 cells." (PMID 36010962, 2022). "Therefore, one has to consider the unfavorable pathological outcome of Arg2 suppression, which might arise due to heightened inflammation in normal adjacent tissue to the tumor, which can exacerbate the development of preneoplastic metaplastic lesions." (PMID 28191010, 2017). "Finally, we evaluated whether the ARG2 expression correlated with the immune cell infiltrate of the primary tumor that we recently published." (PMID 20711410, 2010). "Since ARG2 catalyses the conversion of arginine to ornithine, a crucial metabolite in biosynthesis of glutamic acid, proline and polyamines, an increase in the level of arginase may reflect accelerated metabolism due to cell proliferation or tumour growth." (PMID 14710232, 2004). "For example, HFD induced the expression of arginase (ARG2) in orthotopic PDAC transplant tumors, concordant with higher ARG2 protein levels in tumor biospecimens from high-BMI patients." (PMID 37648285, 2023).
tumor (continued). "The hypoxic TME increases HIF-1α expression in tumor cells, which in turn stimulate inducible nitric oxide synthase (iNOS) and arginase (ARG1 and ARG2) synthesis." (PMID 38259478, 2023). "Overexpression of ARG2 promoted the MMP2/9 expression, further enhancing tumor cell proliferation, migration, invasion and angiogenesis." (PMID 36817446, 2023). "OATD-02 represents a very promising drug candidate for the combined treatment of tumours, and is the only pharmacological tool that can effectively address the benefits of ARG1/ARG2 inhibition." (PMID 36010962, 2022). "One study also demonstrated that the knockout of arginase 2 (ARG2), another enzyme for arginine degradation, can enhance anti-tumor response by coping with unbalanced nutrients." (PMID 36618408, 2022). "ARG2 was revealed to be involved in nitrogen detox and potentially upregulated synthesis of polyamines in highly proliferative PDA tumours." (PMID 36010962, 2022). "A definitive answer on this issue will require comprehensive analysis of paired serum and intracellular citrulline and arginine levels, alongside ARG2 and ASS1 expression, in both tumor and T cells in an in vivo setting." (PMID 33979616, 2021). "The expression of other urea cell cycle genes, such as Arginase-2 (ARG2) and Arginosuccinate synthetase 1 (AAS1), was increased in tumour-resident macrophages as well." (PMID 29422500, 2018). "Similar to ARG2, inhibition of ARG1 expression led to decreased tumor cell proliferation, reduced l-arginine metabolism and reduction of their immunosuppressive potential." (PMID 20711410, 2010). "Arginase 2 (ARG2) is expressed in human PCa and its inhibition, concomitant with iNOS, increases the activation of tumor-infiltrating lymphocytes (TILs)." (PMID 20711410, 2010). "Additionally, they secrete arginase II (Arg2), chitinase-3-like protein 1 (CHI3L1/YKL-40), and the anti-inflammatory cytokines IL-10 and TGF-β, which contribute to their immunosuppressive and tumor-promoting roles." (PMID 40771826, 2025). "By inhibiting ARG-2, OATD-02 was found to regulate the activity of CD8+ cells and Tregs, thus controlling a key player responsible for the metabolic adaptation typical of hypoxic tumours." (PMID 39861764, 2025). "ARG2, one of the genes we found to be upregulated in FLC, could affect cell metabolism in both tumor and immune cells." (PMID 38429349, 2024). "High-endogenous expression of ARG2 in lung SCC xenografts may impede the anti-tumor effect of rhArg1-PEG, but the silencing of ARG2 resensitized H520 xenografts to rhArg1-PEG treatment, partially mediated through arginine depletion via G1 arrest and apoptosis." (PMID 37445845, 2023). "Arginase 2 overexpression has been observed in several cancers, and its inhibition using LMW inhibitors has been shown to suppress growth or promote apoptosis in various tumor cell lines and animal models." (PMID 37749499, 2023). "All tumour types highly expressed SLC7A1 and Arginase, with Arg2 being the main isoform, demonstrating that they could transport and utilise arginine." (PMID 35782058, 2022). "While ARG1 was not expressed at a detectable level in BMDMs and in other brain tissue cells, the expression of ARG2 was present both in macrophages and tumor cells (data not shown)." (PMID 36054818, 2022). "Furthermore, Arg-2 and NOS play important roles in regulating cardiovascular function, the inflammatory response, oxidative stress, immune function, and tumor occurrence and development." (PMID 35283765, 2022). "The growth of K562 tumours was significantly inhibited (final TGI 47%, p = 0.0201 vs. control), implying that OATD-02 arginase inhibitor can directly act on the tumour cells by inhibiting ARG2." (PMID 36010962, 2022). "We concluded that like ARG2 and ASS1, ASL can serve as a metabolic tumor suppressor in ccRCC." (PMID 34861885, 2021).
tumor (continued). "It is probable that in reported cases of PDAC patients, the precise combination of increased ARG2 with a hypoxic TME, characterized by CAIX expression and known for its immunosuppressive properties, contributes to the inhibition of an anti-tumor immune response." (PMID 32707920, 2020). "Given that arginase 2 mRNA was expressed in the healthy tissue and not specifically elevated in the tumor both in our mice and patient tumors, we focused on characterizing arginase 1 expression in CD66b or CXCR2 expressing myeloid cells in the patient tissues." (PMID 30728077, 2019). "Also, arginase II (ARG2) expressed in α-smooth muscle actin (SMA)+ TAF can convert arginine in ornithine, inhibiting tumor infiltrating lymphocyte (TIL) functions; this can happen in hypoxic conditions, impairing the elimination of tumor target cells." (PMID 27834810, 2016). "Both the absolute number of tumor-infiltrating CD3+ T cells and the proportion of Ki-67-positive proliferating cells among the CD3+ T cells observed in the area around ARG2-expressing CAFs were significantly lower than those observed in the other area." (PMID 23424623, 2013). "In prostate tissue samples, ARG2 was more expressed in normal and non-malignant prostatic tissues compared to tumor tissues." (PMID 20711410, 2010). "This androgen-regulated expression was also observed in the primary tumor of ADT-treated patients who expressed less ARG2 in both the non-malignant tissues adjacent to the tumor and the tumor tissues compared to control patients." (PMID 20711410, 2010). "Moreover, the presence of ASS1 in tumour cells correlated with a better prognosis in NSCLC patients, especially when cancer-associated fibroblasts (CAFs) did not express arginase-2 (ARG2)." (PMID 41154605, 2025). "Likewise, expression of ARG1 and ARG2 enzymes in both cancer and immunosuppressive cells leads to the depletion of another important amino acid, L-arginine, from the TME, suppressing T cell–mediated anti-tumor immunity." (PMID 36175673, 2023). "At the same time, there was a large overlap between the genomes of PMN-MDSCs and M-MDSCs involved in immunosuppression, such as IL-1B, ARG-2, CD84, and WFDC17, and chemokine receptors, such as CCR2 and CXCR2, revealing that MDSCs could be migrated to the primary tumor by tumor-derived chemokines." (PMID 34527668, 2021). "Importantly, this increase was only observed in tumors, but not in AsPC1-AKT cells propagated in culture, further highlighting the in vivo, rather than in vitro relevance of ARG2 in PDA tumor growth." (PMID 28808255, 2017). "Arginine depletion therapy with ASS1 inhibition could have a role in the treatment of tumors proficient for arginine synthesis (extensive expression of ASS1 by cancer cells), provided that the tumor stroma does not already play this role by ARG2 overexpression." (PMID 34344457, 2021). "However, we observed that tumor or HR tissues express less ARG2 than non-malignant tissues." (PMID 20711410, 2010). "Note, ARG2 is only expressed in HCC and recent evidence suggest modulation of arginine levels in the extracellular milieu to be part of an immune escape mechanism whereby lack of local arginine weakens tumour-infiltrating lymphocytes as T cells require adequate argine levels." (PMID 25872475, 2015).